MCL1 (MCL1 apoptosis regulator, BCL2 family member)
Diseases named in the same sentence as MCL1 in open-access papers (continued):
Sharing a sentence is not in itself a finding about the gene and the disease.
lymphoma (continued). "Several lines of in vitro evidence suggest that sorafenib might have a role in the treatment of lymphomas by overcoming the cytoprotective effects of ERK, and Mcl-1 and eventually targeting oncogenic signaling pathways driving lymphomagenesis." (PMID 23620775, 2013). "Mcl-1 ubiquitination is thus offset by the activities of USP9X and it has been reported that increased USP9X expression correlates with increased Mcl-1 protein levels and a poor prognosis in lymphoma patients." (PMID 23171055, 2012). "This behaviour is consistent with the agent’s ability to inhibit colony formation of Eμ–myc lymphoma cell lines overexpressing Bcl-2, but not Mcl-1 or A124." (PMID 19079626, 2008). "Additionally, MCL-1 transgenic mice often develop aggressive subtypes of B-cell lymphoma, and MCL-1 is critical for the sustained growth and survival of c-MYC driven lymphoma." (PMID 37919300, 2023). "However, pharmacological inhibition of MCL-1 with AZD5991, in combination with dose-dependent BFL-1 knockdown, induced cell killing, demonstrating that BFL-1 and MCL-1 were crucial for the survival of the lymphoma cells." (PMID 35201512, 2022). "Since protein phosphatase 2A (PP2A) was reported to dephosphorylate MCL1 at Ser159 and Thr163 in its PEST region and prevent its rapid degradation in lymphoma cells, we hypothesized that PP2A may participate in MCL1 stabilization during nab-PTX resistance in ESCC." (PMID 34638252, 2021). "Our three main findings are that a lack of a venetoclax response is primarily a consequence of pro-apoptotic protein dysfunction, the absence of BCL2 protein and the presence of MCL1, the initial finding being a novel feature of lymphomas with high-grade morphology." (PMID 33670870, 2021). "In summary, the BH3 profiling of primary NHLs shown here supports at least three causes of poor venetoclax responses: pro-apoptotic signaling defects, a lack of BCL2 protein expression in high-grade lymphomas, as well as co-dependence on MCL1, observed in all NHL subtypes." (PMID 33670870, 2021). "Loss of miR-29 and decreased levels of miR-125b and miR-133b, miRNA that bind and negatively regulate MCL-1 expression, have been reported in many lymphomas, including Burkitt, anaplastic large cell, and DLBCL, which may also contribute to increased MCL-1 expression." (PMID 30671383, 2018). "To confirm the importance of Bcl-xL in ALCL, we made use of the Piccaluga Lymphoma dataset and observed significant upregulation of BCL2L1 (Bcl-xL) expression when compared to healthy donor T cells, whereas BCL2 and MCL1 were not significantly upregulated." (PMID 36045346, 2022). "Lymphomas in this model lacking Tyk2 have reduced STAT1 and STAT3 phosphorylation and reduced expression of Mcl1, a pro-survival member of the BCL2 family." (PMID 30131584, 2019). "Preclinically, dual targeting of BCL2 and MCL1, but not either alone, was also shown to prolong survival of AML or lymphoma bearing mice." (PMID 30647404, 2019). "The growth of lymphomas is typically supported by the expression of an anti-apoptotic protein; however, MMTV-RARαG303E lymphomas did not express BCL6, BCL2 or MCL1 (Results section), and preliminary data indicated that BCL-XL is weakly expressed." (PMID 16563162, 2006). "Notably, deletion of BAX alone is sufficient to confer resistance to the MCL1 inhibitor S63845 in aggressive lymphoma models, even when BAK is intact, highlighting that BAX plays a non-redundant role in MCL1-dependent cell death." (PMID 41155156, 2025). "Moreover, the absence of BCL-W had no impact on severity of malignant disease, lymphoma immune-phenotype(s), expression of other BCL-2 family members or responses to inhibitors of MCL-1 or BCL-2 + BCL-XL + BCL-W." (PMID 37567974, 2023).
ovarian carcinoma (115 papers, 2011 to 2025). A malignant neoplasm originating from the surface ovarian epithelium. "In line, constitutive BAK/MCL1 complexes were associated with paclitaxel and S63845 response in ovarian cancer PDX models." (PMID 39931207, 2024). "We previously demonstrated that COL11A1-mediated nuclear factor-κB activation promoted the expression of TWIST1 and Mcl-1, factors associated with chemoresistance and anti-apoptosis in ovarian cancer cells." (PMID 30975980, 2019). "Silencing of LINC00152 dramatically declined ovarian cancer cell growth and caused apoptosis in vitro and in vivo by acting as a ceRNA target of miR‐125b to downregulate MCL‐1 expression and induce mitochondrial‐dependent cell death inhibition." (PMID 30030896, 2018). "Because MCL‐1 is a direct target of miR‐125b,14 we further investigated the potential role of miR‐125b‐mediated regulation of MCL‐1 in ovarian cancer and its association with LINC00152." (PMID 30030896, 2018). "Actually, Bcl-xL and Mcl-1 are often overexpressed in ovarian carcinoma and are associated with poor prognosis in these cancers." (PMID 25627260, 2015). "Both Bcl-xL and Mcl-1 have been implicated to protect ovarian cancer cells from chemotherapy-induced apoptosis, their concomitant decrease appearing essential to trigger the cell death." (PMID 26063499, 2015). "As observed in the present study for Mcl-1 isoforms, high Mcl-1 protein expression and its association with poor prognosis has been demonstrated in cervical, gastric, lung and ovarian cancers." (PMID 25409302, 2014). "Our previous work showed that platinum resistance was associated with the capacity of ovarian cancer cells to maintain a high level of two anti-apoptotic proteins of the Bcl-2 family, Bcl-xL and Mcl-1." (PMID 23735052, 2013). "Numerous studies have reported that high MCL-1 expression is linked to the occurrence, progression, metastasis, and poor prognosis of various tumors, including human breast, renal, hepatocellular, gastric, pulmonary, ovarian cancers, and lymphoma." (PMID 39012900, 2024). "Besides, IL-6 induces the Mcl-1 anti-apoptotic protein expression, which is recurrently overexpressed in ovarian cancer, and it is associated with advanced tumor grade and poor survival in epithelial ovarian cancer." (PMID 34751020, 2022). "For instance, miR-106a targeting MCL1 to inhibit cisplatin resistance of A2780 in ovarian cancer cells implies a Type-4 association between miR-106a and ovarian cancer; the feedback loops between miR-124 and TGF-β pathways play an important role in metastasis of non-small cell lung cancer." (PMID 34572337, 2021). "Thus, the association between the constitutive presence of BAK/MCL1 complexes and paclitaxel sensitivity also extended to ovarian cancer PDX models." (PMID 34385422, 2021). "In conclusion, the effect of citrate on Mcl-1 expression could usefully be associated with inhibitors of Bcl-xL, since this strategy demonstrates a strong anti-cancer effect on chemoresistant ovarian cancer cells." (PMID 24103422, 2013). "LA’s growth-inhibitory effect in the ovarian cancer cells is linked to the lengthening of the half-life of the cyclin-dependent kinase inhibitor, p27kip1 and downregulation of two anti-apoptotic proteins, Mcl-1 and Bcl-xL protein and a strong induction of the BH3-only protein Bim." (PMID 37087461, 2023). "This is in part because paclitaxel can inhibit MCL-1 transcription and translation via induction of mitotic arrest, which makes ovarian cancer cells highly sensitive to DT2216-induced BCL-xL degradation." (PMID 41225624, 2025). "Previously, we showed that ovarian cancer cell apoptosis can be triggered by inhibiting the anti‐apoptotic proteins Bcl‐xL and Mcl‐1 and/or by inducing their pro‐apoptotic partners Bim, Puma, and Noxa." (PMID 40483575, 2025). "We first explored the apoptotic potential of combining Mcl‐1 inhibition with belinostat at cytostatic concentration in our ovarian cancer cell lines." (PMID 40483575, 2025).
ovarian carcinoma (continued). "To conclude, our study underlines the anticancer potential of belinostat, used alone or combined with Bcl‐xL or Mcl‐1 inhibitors, in preclinical models of ovarian cancer." (PMID 40483575, 2025). "Analysis of ONCOMINE dataset revealed that paclitaxel-resistant ovarian cancer patients showed significantly higher expression of anti-apoptotic genes (Mcl-1, Bcl-2, Bcl-xL, and PARP) compared to paclitaxel-sensitive patients (P < 0.01)." (PMID 40599869, 2025). "More specifically, our previous work has shown that the survival of ovarian cancer cells relies on the cooperation between Bcl‐xL and Mcl‐1 anti‐apoptotic proteins to sequester their pro‐apoptotic partners." (PMID 40483575, 2025). "Our previous work has shown that in ovarian cancer cells, the threshold for triggering apoptosis can be reached by reducing the [Bcl‐xL and Mcl‐1]/[Bim, Puma, and Noxa] ratio." (PMID 40483575, 2025). "Analysis of genomic data from The Cancer Genome Atlas (TCGA) indicated high Mcl-1 protein expression in several cancer types, including lung, breast, colon, ovarian carcinomas, gastric, multiple myeloma, non-small-cell lung cancer, and malignant melanoma." (PMID 38928234, 2024). "For instance, sodium citrate, an anti-glycolytic agent, was found to reduce the expression level of Mcl-1 in ovarian carcinoma cells." (PMID 38390269, 2024). "Pancreatic and ovarian cancers have both been shown to have amplified levels of MCL1, with one of the mainstay therapies being platinum-based reagents." (PMID 37760451, 2023). "Another study showed that the dual PI3K/mTOR inhibitor NVP-BEZ235 downregulated Mcl-1 and thereby inhibited the growth of ovarian cancer cells." (PMID 35783514, 2022). "The miR-15a-3p has been shown to suppress proliferation and migration inhibiting the expression of BCL2 and MCL1 in epithelial cells and restrains the growth and metastasis of ovarian cancer cells by regulating Twist1." (PMID 36012492, 2022). "For example, BAG3 can upregulate MCL1 by downregulating miR-29b, thereby inducing chemotherapy resistance to paclitaxel in ovarian cancer." (PMID 36262872, 2022). "USP13 also functions as an oncogene by stabilizing MCL1 apoptosis regulator (MCL1) in lung and ovarian cancer cells." (PMID 35173307, 2022). "For instance, the dual PI3K/mTOR inhibitor PKI-402 inhibits the growth of ovarian cancer cells via degradation of Mcl-1." (PMID 35783514, 2022). "For instance, miR-153-3p modulates development of ovarian cancer in vivo and in vitro via targeting MCL1 gene." (PMID 35266447, 2022). "Unlike USP9X, which exhibits tissue-specific expression primarily in the brain and immune system, USP13 regulates MCL1 turnover in lung and ovarian cancers." (PMID 36551253, 2022). "In this study, we found that the presence of preformed BAK/MCL1 complexes in ovarian cancer significantly correlates with S63845 and paclitaxel sensitivities." (PMID 34385422, 2021). "Here, we have shown that the presence of preformed BAK/MCL1 complexes is a predictor of paclitaxel sensitivity in ovarian cancer cell lines and PDX." (PMID 34385422, 2021). "Taken together, these data suggest that the paclitaxel/S63845 combination also inhibits ovarian cancers with BAK/MCL1 complexes in vivo at achievable drug concentrations." (PMID 34385422, 2021). "In summary, we have found that pre-existing BAK/MCL1 complexes contribute to apoptotic sensitivity of ovarian cancer to paclitaxel, S63845 and the combination." (PMID 34385422, 2021). "MCL-1, another BCL-2 family member associated with resistance to BCL-2-targeted agents, also mediates chemoresistance in ovarian cancer." (PMID 34351305, 2021). "Our results suggest that the pre-formed BAK/MCL1 complexes not only correlate with sensitivity to paclitaxel and S63845 in ovarian cancer cells but also predict synergy of the paclitaxel/S63845 combination." (PMID 34385422, 2021). "Myeloid cell leukemia sequence 1 (MCL1) plays a critical role in the regulation of chemoresistance in ovarian cancer." (PMID 34454495, 2021).
ovarian carcinoma (continued). "Amplifications of MCL1 are observed in several human cancers such as breast, lung, and ovarian cancers." (PMID 33670375, 2021). "Although our results have demonstrated an important role of pre-formed BAK/MCL1 complexes in sensitizing ovarian cancer cells to paclitaxel, S63845, and the combination, there are also some limitations of our study." (PMID 34385422, 2021). "Here we show the relative amount of BAK found in preformed complexes with MCL1 or BCLXL varies across ovarian cancer cell lines and patient-derived xenografts (PDXs)." (PMID 34385422, 2021). "Increasing the [BH3-only Bim, Puma, Noxa proapoptotic]/[Bcl-xL, Mcl-1 antiapoptotic] proteins ratio was proven to efficiently kill ovarian carcinoma cells and development of new molecules to imbalance Bcl-2 member equilibrium are strongly required." (PMID 32424251, 2020). "Myeloid cell leukemia 1 (MCL1), which is an antiapoptotic protein in ovarian cancer, allows cancer cells to evade apoptosis when its expression is upregulated." (PMID 33061844, 2020). "This evidence suggests that Mcl-1 stability is crucial for ovarian cancers to halt the progression of the cell death pathway, but more research needs to be done to determine the full scope of Mcl-1 protein:protein interactions." (PMID 33182737, 2020). "Collectively, these findings supported that USP13 and MCL1 were concomitantly overexpressed in human lung and ovarian cancer to promote tumorigenesis." (PMID 29335437, 2018). "Our group previously showed that the anti-apoptotic proteins Mcl-1 and Bcl-xL were able to cooperate to allow ovarian carcinoma cells to overcome apoptosis, as their concomitant inhibition was sufficient to induce cell death." (PMID 30338034, 2018). "Here we perform an unbiased siRNA screen and identify that the second deubiquitinase, USP13, regulates MCL1 stability in lung and ovarian cancer cells." (PMID 29335437, 2018). "Above all, functional recovery experiments proved that silencing of LINC00152 resulted in a significant decrease in growth in ovarian cancer, and this regulation occurred via MCL‐1 and is abolished by miR‐125b inhibitors." (PMID 30030896, 2018). "To determine the protein expression and relatedness of USP13 and MCL1 in patients, we performed immunohistochemical (IHC) staining of human lung and ovarian cancer tissues." (PMID 29335437, 2018). "To further evaluate its impact on drug sensitivity in ovarian cancer cells, we screened a collection of 180 small-molecule inhibitors targeting wide-ranging signaling pathways using MCL1-depleted SW-1573 cells." (PMID 29335437, 2018). "The results indicated that LINC00152 regulates the ovarian cancer growth via competitive binding of miR‐125b to MCL‐1." (PMID 30030896, 2018). "We concluded that USP13 promoted MCL1 stability at the post transcriptional level in lung and ovarian cancer cells." (PMID 29335437, 2018). "As Bcl-xL and Mcl-1 cooperate to protect ovarian carcinoma cells from apoptosis, we next evaluated the efficacy of SOCE inhibitor/anti-BclxL strategies." (PMID 30338034, 2018). "Our objective was then to test the effect of CAI, a calcium inhibitor used in clinical trials, on Mcl-1 expression and to evaluate its ability to sensitize ovarian carcinoma cells to anti-Bcl-xL strategies." (PMID 30338034, 2018). "The anti-apoptotic proteins Bcl-xL and Mcl-1 have been identified to play a pivotal role in apoptosis resistance in ovarian cancer and constitute key targets for innovative therapeutic strategies." (PMID 30338034, 2018). "CAI had an anti-proliferative effect on ovarian carcinoma cell lines and strongly down-regulated Mcl-1 expression." (PMID 30338034, 2018). "Dinaciclib alters the expression of apoptosis proteins, including Mcl-1, Bcl-xL and survivin, and induces apoptosis in ovarian cancer and osteosarcoma cells." (PMID 28207834, 2017).
ovarian carcinoma (continued). "Strikingly, PUMA-induced downregulation of Bcl-xL and Mcl-1, which was similar to our previous observations in ovarian cancer cells, were partially rescued by JNK inhibitor SP600125." (PMID 28423586, 2017). "These inhibitors have the ability to dissociate Mcl-1 from Bim in whole living cells and acquired sensitivity ovarian cancer cells to Bcl-X and increased cell death." (PMID 29100389, 2017). "In-depth analysis of BCL-2 family proteins and other apoptotic regulators in response to PI3K/mTOR pathway blockade identifies BIM, caspase-3, BCL-XL, XIAP, and MCL-1 as critical players in ovarian cancer cell survival." (PMID 28848242, 2017). "For instance, ovarian cancer cells exposed to BAPTA-AM display a reduction in the protein levels of anti-apoptotic Mcl-1." (PMID 29340082, 2017). "Our results showed that Mcl-1 is a crucial resistant factor against DCA-induced apoptosis in ovarian cancer cells, and cotreatment with Met and DCA decreased Mcl-1 and enhanced apoptosis." (PMID 27449090, 2016). "These authors also showed that sensitivity to anti-mitotic agents was regulated by FBXW7 through degradation of MCL1 in colon and ovarian cancer cells." (PMID 27409838, 2016). "We found that CHI3L1 interfered with the paclitaxel-induced apoptosis of human ovarian cancer cells by up-regulating the anti-apoptotic Mcl-1 molecule." (PMID 26452028, 2015). "In vitro studies showed that CHI3L1 up-regulated the expression of anti-apoptotic Mcl-1 protein and hampered paclitaxel-induced apoptosis of ovarian cancer cells." (PMID 26452028, 2015). "As Bcl-xL and Mcl-1 cooperates to prevent ovarian carcinoma cells from apoptosis, we next evaluated the efficacy of BAPTA-AM/anti-BclxL strategies combinations." (PMID 25627260, 2015). "Our in vitro experiments also show that CHI3L1 can promote ovarian cancer cell resistance to paclitaxel by up-regulating Mcl-1." (PMID 26452028, 2015). "We previously demonstrated that ovarian carcinoma cells are addicted to Bcl-xL and Mcl-1 anti-apoptotic members and that these two proteins cooperate to compromise chemosensitivity." (PMID 25627260, 2015). "The PI3K/mTOR dual inhibitor NVP-BEZ235 reduced Mcl-1 expression and sensitized ovarian carcinoma cells to ABT-737 through a Bim-dependent mechanism." (PMID 26405162, 2015). "Leptin has been shown to activate PI3K/Akt and ERK1/2 survival pathways and stimulate the expression of anti-apoptotic protein Mcl-1 in ovarian cancer cell line OVCAR3." (PMID 26122176, 2015). "We previously showed that Bcl-xL and Mcl-1 cooperatively protect platinum-resistant ovarian cancer cells from apoptosis." (PMID 25627260, 2015). "To assess the possible involvement of PKC in calcium-mediated Mcl-1 regulation, we treated ovarian carcinoma cells with a specific PKC inhibitor, GF109203X." (PMID 25627260, 2015). "This pathway is the most frequently deregulated pathway in ovarian cancer and it is also known to regulate Mcl-1 translation focusing research to target this network in order to sensitize cancer cells." (PMID 25627260, 2015). "In ovarian carcinoma, we previously demonstrated that Bcl-xL and Mcl-1 cooperate to protect tumor cells against apoptosis and their concomitant inhibition leads to massive apoptosis even in absence of chemotherapy." (PMID 26712767, 2015). "This resulted in the decreased expression of STAT3 downstream targets such as Mcl-1 and sensitization of paclitaxel-resistant ovarian cancer cell lines to chemotherapy." (PMID 24782986, 2014). "Concomitant inhibition of Mcl-1 and Bcl-xL is a highly effective strategy to destroy chemoresistant ovarian cancer cells, in accordance with previous studies we have conducted on cancer cells from other cancer sites." (PMID 24103422, 2013). "Here we investigated the cytotoxic activity of MR22388 on cisplatin-resistant ovarian carcinoma cells and its potential as a modulator of the expression or activity of Bcl-xL and Mcl-1." (PMID 23735052, 2013).